INS (insulin)
Diseases named in the same sentence as INS in open-access papers (continued):
Sharing a sentence is not in itself a finding about the gene and the disease.
type 2 diabetes (continued). "In contrast to type 1 diabetes, which is related to autoimmune destruction of pancreatic β cells, leading to absolute insulin deficiency, type 2 diabetes development involves impaired pancreatic β cell function, insulin resistance and inflammation." (PMID 22347618, 2012). "Loss of first-phase insulin secretion has been well characterised as a primary defect in the development of type 2 diabetes." (PMID 22815837, 2012). "In humans the rs13266634 polymorphism in the SLC30A8 gene has been linked to not only type 2 diabetes but also impaired glucose tolerance, impaired proinsulin to insulin conversion and reduced first phase insulin secretion." (PMID 22829903, 2012). "Genome-wide association studies have identified hundreds of loci for type 2 diabetes, coronary artery disease and myocardial infarction, as well as for related traits such as body mass index, glucose and insulin levels, lipid levels, and blood pressure." (PMID 22876189, 2012). "Chronically high levels of cortisol can impair insulin sensitivity and disrupt glucose metabolism, increasing the risk for type 2 diabetes." (PMID 22844441, 2012). "Endogenous levels of estradiol are positively associated with insulin and glucose and with type 2 diabetes, although exogenous estrogen replacement has been shown to increase insulin sensitivity and decrease the risk of type 2 diabetes." (PMID 22448212, 2012). "In fact, in observational studies metformin therapy in insulin-treated patients with type 2 diabetes is associated with reduced cancer incidence even after adjusting for insulin doses." (PMID 23209929, 2012). "HM adiponectin possesses the most potent insulin-sensitizing activity and is more closely associated with the development of type 2 diabetes than total adiponectin." (PMID 22496878, 2012). "The possibility of an association between insulin therapy and cancer in type 2 diabetes has prompted a wide and interesting discussion in the scientific community, stimulating both basic and clinical research." (PMID 23209929, 2012). "An attenuated response to insulin stimulation is causally related to obesity, type 2 diabetes, and metabolic syndrome, and improved whole-body insulin sensitivity is important in the treatment of these metabolic disorders." (PMID 22754566, 2012). "It would be of particular interest to include the insulin signalling pathway in order to explore the connection between AD and type 2 diabetes since GSK3β has been implicated in both diseases." (PMID 22482080, 2012). "Type 2 diabetes is caused by a combination of insulin resistance in the adipose tissue, liver and skeletal muscle and impaired insulin secretion from the pancreatic islets." (PMID 22272317, 2012). "Since beta cell failure is the key event in the transition from an insulin resistant state associated with normal glucose tolerance to type 2 diabetes these observations are consistent with an important role for ZnT-8 in beta cell function." (PMID 22829903, 2012). "There is continuing debate concerning the risk of cancer and the association with insulin use in patients with type 2 diabetes." (PMID 21410860, 2011). "It has been suggested that vitamin D insufficiency decreases insulin sensitivity in this way and also increases the risk of type 2 diabetes." (PMID 22155462, 2011). "ADIPOQ, encoding adiponectin, is a candidate gene for type 2 diabetes (T2D) identified by genome-wide linkage analyses with supporting evidence showing the protein function in sensitizing insulin actions." (PMID 22046359, 2011). "High circulating concentrations of insulin and C-peptide, as well as type 2 diabetes, are associated with increased risk of CRC." (PMID 21559014, 2011). "As glucocorticoids increase, insulin secretion also increases, as it is well known from the strong association of Cushing's syndrome with type 2 diabetes." (PMID 21949667, 2011).
type 2 diabetes (continued). "Insulin is an important growth factor in utero, potentially providing a common mechanism linking reduced foetal growth with increased risk of type 2 diabetes." (PMID 21949744, 2011). "The primary cause of hypoglycemia among patients with type 2 diabetes is antihyperglycemic medications - in particular, those which raise insulin levels independently of blood glucose, such as sulfonylureas and insulin." (PMID 21777428, 2011). "In humans, dysregulation of TGF-β signaling and the insulin/IGF-1 signaling axis have been implicated in the onset of age-associated diseases such as Type 2 Diabetes and cancer." (PMID 21533078, 2011). "Type 2 diabetes is a progressive disease characterized by ongoing loss of β-cell function leading to oral agent failure and the need for insulin-replacement therapy." (PMID 21812890, 2011). "This SNP was 568kb to the transcription start site of NOTCH2, a gene associated with insulin release, insulin sensitivity, obesity and type 2 diabetes." (PMID 21738711, 2011). "Alteration of plasma lipoprotein profile, with increased risk of cardiovascular diseases, decreased insulin sensitivity, and higher risk of type 2 diabetes, has been reported to follow the long-term intake of TFAs." (PMID 21266050, 2011). "Activation of the IGF-1R by insulin can also significantly contribute to an increased risk of cancer in patients with type 2 diabetes." (PMID 22203527, 2011). "Plasma FFA levels are commonly associated with impaired insulin-mediated glucose uptake in related tissues, and coexist with type 2 diabetes and obesity." (PMID 21716679, 2011). "Genetic variants that influence fetal insulin secretion or insulin sensitivity appear to be important determinants of fetal growth, and subsequent development of type 2 diabetes." (PMID 21712988, 2011). "There are studies in adults reporting that vitamin D deficiency affects insulin sensitivity negatively and increases the risk for type 2 diabetes mellitus." (PMID 22155462, 2011). "The objective of this study was to characterize insulin use and examine factors associated with persistence to mealtime insulin among patients with type 2 diabetes (T2D) on stable basal insulin therapy initiating mealtime insulin therapy." (PMID 21226935, 2011). "Type 2 diabetes is a progressive disease and the usual natural history is of progressive loss of insulin secretory capacity over time and the need for intensification of therapy and polypharmacy." (PMID 21480973, 2011). "Type 2 diabetes is associated with two principal physiological defects: resistance to the action of insulin and deficiency in insulin secretion." (PMID 21935427, 2011). "The intracellular signaling mechanisms regulating insulin secretion have been extensively studied, and transcription factors have been linked to β-cell dysfunction in type 2 diabetes and maturity-onset diabetes of the young." (PMID 21949805, 2011). "The importance of IDE in regulating insulin metabolism became evident from studies of the GK rat model of type II diabetes mellitus where variants of IDE with reduced catalytic activity were found to be associated with elevated insulin levels." (PMID 21731629, 2011). "Our study provides the first evidence that SNP rs1241321 in DDAH1 is associated with insulin sensitivity, type 2 diabetes and their long-term prognosis, independently of plasma ADMA levels." (PMID 21303562, 2011). "Increased bodyweight correlates inversely with insulin sensitivity and overall metabolic status, which in turn affects the risk of type 2 diabetes and of cardiovascular diseases." (PMID 20209148, 2010). "The condition describes a clustering of cardiovascular risk factors in patients with insulin-resistant states, including obesity, hypertension, coronary heart disease and/or type 2 diabetes." (PMID 21532777, 2010).
type 2 diabetes (continued). "Abnormalities in carbohydrate and fat metabolism are characteristic of insulin-resistant tissues, and are implicated in elevated plasma sugar and fatty acid levels in patients with type II diabetes." (PMID 20952811, 2010). "It is a well established fact that type 2 diabetes is caused by the interplay of a triad which includes the progressive decline in insulin producing β-cells, an increase in insulin resistance and increased hepatic glucose production." (PMID 20673334, 2010). "Extensive evidence now also points to a strong association between hepatic and skeletal muscle insulin resistance and dysregulation of whole body glucose homeostasis and fasting hyperglycemia in type-2 diabetes." (PMID 20433743, 2010). "CgB-deficiency in mice leads to a phenotype with some hallmarks of human type-2 diabetes including loss of the initial rapid phase of insulin secretion and hypersecretion of proinsulin." (PMID 20126668, 2010). "These abnormalities are the hallmark of many insulin-resistant states, such as the metabolic syndrome and the common form of type 2 diabetes." (PMID 21532777, 2010). "As a result, glucose stimulation of insulin exocytosis is impaired causing hyperglycemia, a clinical hallmark of type 2 diabetes." (PMID 20066028, 2010). "Type 2 diabetes and decreased insulin sensitivity are associated with the production of advanced glycation end products (AGE), which trigger inflammatory cytokine production, thus predisposing to inflammatory diseases such as periodontitis." (PMID 21691545, 2010). "Treatment with the amylin analog pramlintide is associated with improved weight control in patients with type 2 diabetes when administered with insulin therapy." (PMID 20804556, 2010). "African Americans (AA) have lower insulin sensitivity and, subsequently, a greater risk of type 2 diabetes compared to European Americans (EA), although the cause of this disparity is multi-factorial and not completely understood." (PMID 20398267, 2010). "In this study, we found that pancreatic β cells from mice null for CDKAL1, which was identified as a susceptibility gene for type 2 diabetes in humans, have a reduced first-phase insulin release in vitro." (PMID 21151568, 2010). "Metabolic syndrome is the major predisposing factor to type 2 diabetes, where defects in both insulin action and insulin secretion are present, but their relative contribution varies individually." (PMID 20480025, 2010). "A decline in body insulin sensitivity in apparently healthy individuals indicates a high risk to develop type 2 diabetes." (PMID 20976215, 2010). "Several studies have found that exercise independently decreases glucose levels and risk of type 2 diabetes, and calorie restriction independently lowers insulin and triglyceride levels." (PMID 20550839, 2010). "Effects of SNPs from fifteen glucose and insulin loci on type 2 diabetes susceptibility in the Chinese population." (PMID 21103350, 2010). "At present, when people with type 2 diabetes have poor control on a combination of oral agents, the usual next step is to start insulin treatment, which often causes weight gain and hypoglycaemia, and often does not achieve good control." (PMID 21143938, 2010). "The higher prevalence of type 2 diabetes observed among S319 carriers is likely explained by the compromised ability of these subjects to mount an adequate insulin response, resulting in an earlier loss of glycemic control." (PMID 20716378, 2010). "Type 2 diabetes is a progressive continuing metabolic disorder characterised by hyperglycaemia caused by insulin deficiency usually on a background of insulin insensitivity." (PMID 20946269, 2010). "Adults of African-Caribbean origin living in the UK have smaller increases in type 2 diabetes risk, raised circulating insulin and HDL-cholesterol, and low triglyceride and C-reactive protein concentrations." (PMID 20421924, 2010).
type 2 diabetes (continued). "NAFLD affects 20-30% of the general Western population, and the condition is strongly associated with insulin resistant states such as obesity, metabolic syndrome and type 2 diabetes mellitus (T2DM)." (PMID 20353583, 2010). "PPARα agonists lower plasma lipid levels, decrease intrahepatic and muscle lipid accumulation, normalize glucose and insulin levels, and reduce the risk of type 2 diabetes in rodent models." (PMID 20825652, 2010). "Progression of type II diabetes is mainly due to loss of pancreatic β-cell function, which results in increased impairment of patient’s ability to produce insulin in response to increased blood glucose." (PMID 20927247, 2010). "The insulin (INS) gene locates at chromosome 11p15.5 and is one of established susceptibility locus to type II diabetes in Caucasians." (PMID 19948072, 2009). "Type 2 diabetes is a complex disease characterized by elevated blood glucose, caused mainly by impairment in both insulin action and beta cell function." (PMID 19862325, 2009). "Type 2 diabetes is becoming widely recognized as a risk factor for AD development and features like insulin signaling defects, Aβ accumulation and hyperphosphorylation of tau protein are possible contributors to this relation." (PMID 27713238, 2009). "Their pharmacological action is through the reduction of insulin resistance by sensitizing muscle, liver, and adipose tissue to insulin, and treatment is associated with delayed progression to type 2 diabetes." (PMID 19635160, 2009). "In insulin-naïve patients with type 2 diabetes, glargine treatment combined with OADs is associated with significantly lower HbA1c levels and fewer episodes of symptomatic hypoglycaemia compared with premix." (PMID 19220880, 2009). "In conclusion, we report insulin sensitivity independent impairment of insulin release following an oral glucose load in a large population of middle-aged treatment naïve individuals carrying the type 2 diabetes associated minor C-allele of KCNQ1 rs2237895." (PMID 19516902, 2009). "Although association between rs12255372 and risk of Type 2 diabetes is thought to be due to impairment of insulin secretion, TCF7L2 has also long been known to have a role in Wnt/β-catenin signaling." (PMID 19732438, 2009). "The association of the VNTR polymorphism in 5-prime flanking region of the INS gene susceptible to type II diabetes with PCOS have been studied over the years in different populations, and the results observed have been inconsistent and controversial." (PMID 19948072, 2009). "Elevated fasting plasma glucose in type II diabetes mellitus is known to be frequently associated to elevated plasma levels of plasma insulin." (PMID 19180194, 2009). "This corresponds with the altered insulin sensitivity that has been associated with better glycemic control in patients with type 2 diabetes, but also in critically ill patients treated with IIT." (PMID 19589139, 2009). "Including improvements in functional capacity, fasting insulin levels, and reduce risk of Type 2 diabetes." (PMID 18655709, 2008). "It has been proposed that stress activates the hypothalamo–pituitary–adrenal axis and the central sympathetic system and leads to the development of endocrine perturbation and obesity, which increases insulin resistance, causing Type 2 diabetes." (PMID 19046200, 2008). "Type 2 diabetes is a highly prevalent, progressive disease, characterized by defects in insulin production and utilization and is associated with significant morbidity and mortality." (PMID 18279520, 2008). "A decline of IRS-1 amount or function has been linked to decreased glucose uptake in insulin resistant animal models and type II diabetic patients." (PMID 19787081, 2008). "Deficiency of a single circulating protein i.e. insulin underlies type 1 diabetes and is a significant abnormality in the later stages of type 2 diabetes." (PMID 18320053, 2008).
type 2 diabetes (continued). "Failure of the adipocyte and other target cells to properly respond to insulin, insulin resistance, is often associated with obesity and is a distinguishing feature of type 2 diabetes." (PMID 18551197, 2008). "For the same degree of blood glucose reduction, metformin treatment is associated with a lower risk of hypoglycaemia than with insulin secretagogues and insulin treatment in patients with type-2 diabetes." (PMID 18852875, 2008). "Type 2 diabetes arises when insulin resistance cannot be compensated for with increased insulin secretion owing to a gradual loss of pancreatic beta-cell function." (PMID 18985156, 2008). "Chronic elevation in plasma FFA levels is commonly associated with impaired insulin-mediated glucose uptake in skeletal muscles and often coexists with obesity and type 2 diabetes." (PMID 18523557, 2008). "Overweight and obesity have also been related to low levels of the insulin sensitiser adiponectin, and consequently to increased risk of hyperinsulinaemia and type II diabetes." (PMID 17912243, 2007). "A recent study identified genetic association of type 2 diabetes (T2D) with this gene, correlated with diminished insulin secretion." (PMID 17683561, 2007). "Correct intracellular trafficking of the InsR is critical for insulin sensitivity and it has been shown that mutations in the InsR gene that impair the transport of the receptor to the plasma membrane lead to type 2 diabetes in humans." (PMID 17987120, 2007). "We examined the association between race/ethnicity and cardiovascular disease risk factor control in a large cohort of insulin-treated veterans with type 2 diabetes." (PMID 16716235, 2006). "We were unable to confirm a role for nonsynonymous variants of betacellulin in the propensity to type 2 diabetes or to impaired insulin secretion." (PMID 16869959, 2006). "We evaluated racial/ethnic differences in glycemic control, medical therapy, and control of cardiovascular disease risk factors in insulin-treated Southwest American veterans with type 2 diabetes." (PMID 16716235, 2006). "Defects in glucose transport have been implicated in the reduced insulin sensitivity and in the increased insulin resistance observed in type 2 diabetes." (PMID 16336637, 2005). "Decreased concentrations of adiponectin are associated with type 2 diabetes, hypertension, elevated glucose levels, insulin and TGs, and cardiovascular disease (CVD)." (PMID 15530168, 2004). "Despite the current diagnostic criteria for type 2 diabetes primarily focusing on glycemia, its development is attributed to abnormalities in insulin secretion, action or metabolism that may be altered even when still in normoglycemia." (PMID 41133433, 2026). "Excess adiposity is a particular overarching challenge in the treatment of type 2 diabetes because weight control can benefit so many of the other unmet needs by reducing metabolic stress to beta cells, improving insulin sensitivity and independently reducing the risk of associated morbidities." (PMID 41174263, 2026). "We created an in vitro model to understand the disparate mechanisms whereby this KATP channel variation causes hyperinsulinaemia in utero and in infancy yet increases risk of type 2 diabetes, a disease characterised by impaired insulin secretion, later in life." (PMID 41291239, 2026). "Consistently, evidence from previous studies indicates that achieving prediabetes remission through lifestyle-induced weight loss of over 7% significantly improves insulin sensitivity and beta cell function, resulting in a 73% reduction in the type 2 diabetes risk." (PMID 41107618, 2026). "This may be because type II diabetes is due to impaired glucose tolerance and pancreatic diabetes is due to impaired insulin secretion caused by endocrine dysfunction, and the present marker reflects impaired exocrine function, which is a different mechanism." (PMID 40227633, 2025).